NRAS (NRAS proto-oncogene, GTPase)
Diseases named in the same sentence as NRAS in open-access papers (continued):
Sharing a sentence is not in itself a finding about the gene and the disease.
melanoma (continued). "Treatment of NRASQ61 melanoma with the MEK inhibitor, binimetinib (MEK162), is currently in clinical trial and is the only targeted treatment for NRAS mutant melanomas." (PMID 27447557, 2016). "Pharmacological inhibition of IFI6 expression by the MEK inhibitor trametinib, when combined with DNA replication stress-inducing drugs, blocked NRAS-mutant melanoma growth." (PMID 27608486, 2016). "These transformed melanoblasts are null for INK4a, express mutant NRas under a melanoblast-specific promoter, and form melanomas in syngeneic host mice." (PMID 26948875, 2016). "We found that NRAS-mutant melanoma cells were significantly more resistant to the cytotoxic effects of DNA replication stress-inducing drugs compared to other genotypes (BRAF-mutant, NF1-deficient, or triple wild-type)." (PMID 27608486, 2016). "Four of the melanomas had BRAFV600E mutations, three had NRAS mutations, three had NF1 mutations and one had a MAP2K1 (MEK1) mutation." (PMID 27545456, 2016). "In melanoma the TERT promoter mutations occur together with BRAF and NRAS mutations more frequently than per chance, suggesting a link between TERT expression and MAPK pathway activation during immortalization of melanocytes via ETS proteins." (PMID 27449293, 2016). "Knockdown of IFI6 increased the sensitivity of NRAS-mutant melanoma to DNA replication stress-inducing agents, and simultaneous loss of E2F2 and IFI6 rescues this effect." (PMID 27608486, 2016). "More important, targeting NRAS by MEK inhibitors MEK162 (Binimetinib) was shown to be efficient in a phase II clinical trial with 30 melanoma patients." (PMID 26821351, 2016). "The identification of novel compounds specifically targeting the NRAS-mutant signaling pathway represents a current emerging challenge for the treatment of these melanomas." (PMID 27833586, 2016). "Other frequent genomic alterations in melanoma include deletion or inactivating mutations of PTEN and CDKN2A, amplifications or activating mutations of NRAS, AKT, CCND1, MITF, KIT, and TERT, among others." (PMID 27655717, 2016). "There is an additional need for novel therapies and approaches to the treatment of BRAF wild-type melanomas including NRAS mutant melanoma." (PMID 27447557, 2016). "The MAPK pathway plays a major role in melanoma proliferation and survival and is activated in the majority of melanoma tumors through mutations in BRAF and to some extent in NRAS." (PMID 27449293, 2016). "In this report, we show that IFI6 regulates oncogenic NRAS-induced melanocyte transformation and NRAS-mutant melanoma tumor growth." (PMID 27608486, 2016). "Recent data show that mutations in genes responsible for common nevi or melanomas such as BRAF, NRAS, or c-kit are actually rare in blue nevi." (PMID 27313934, 2016). "These two melanoma cell types, both carrying the point mutation of V600 (exon 15) in BRAF gene and wild type sequence of hot-spot regions exon 1 and 2 in NRAS gene, were then seeded and cultivated separately." (PMID 27175588, 2016). "This genetically vulnerable pathway can be targeted pharmacologically by combining a MEK inhibitor with cytotoxic agents that induce DNA replication stress to potently inhibit NRAS-mutant melanoma growth." (PMID 27608486, 2016). "Cumulatively, based on these findings, we propose a model detailing the rationale for the dual targeting of AURKA and MAPK signaling in melanomas harboring the constitutively active BRAF(V600E) or NRAS (Q61R)." (PMID 26962685, 2016). "Collectively, these results demonstrate that IFI6 is necessary for NRASQ61K-induced transformation and NRAS-mutant melanoma growth." (PMID 27608486, 2016). "To test this, we knocked down IFI6 in NRAS-mutant melanoma cell lines, YUGASP, M318, and SKMEL-103, and measured well-accepted markers of cellular senescence including senescence-associated β-gal (SA-β-gal) and acetylated histone H3K9 (H3K9Ac)." (PMID 27608486, 2016).
melanoma (continued). "Many studies explore the potential use of dual inhibition of MAPK and PI3K/AKT/mTOR which results in growth inhibition in NRAS mutant melanoma and neuroblastoma." (PMID 26821351, 2016). "In addition, immune checkpoint inhibitors have been shown to significantly improve melanoma patient survival, and it is notable that better response rates to immune checkpoint inhibitors have been reported in melanomas with high mutation loads, particularly those containing NRAS mutations." (PMID 27191502, 2016). "The co-occurrence of an NRAS and an SF3B1 mutation in the CNS melanoma of the neurocutaneous melanocytosis patient in our study is interesting in this respect as the SF3B1 mutation was absent in the congenital melanocytic nevus of this patient." (PMID 26769193, 2016). "To discover and develop more effective approaches to treat NRAS-mutant melanoma, we aimed to understand the mechanism of oncogenic NRAS-induced transformation and tumor maintenance." (PMID 27608486, 2016). "Melanomas with no detectable BRAF or NRAS mutations were more common in head and neck melanomas (19.8%) compared to either BRAF (10.0%) or NRAS (8.9%) mutant melanomas." (PMID 27191502, 2016). "The majority of melanomas carry mitogen-activated protein kinase (MAPK) pathway-activating mutations, especially in BRAF, NRAS, NF1; providing avenues for targeted therapeutic intervention." (PMID 27009863, 2016). "The same relationship likely applies to melanoma cell lines as well, since most of these tumors harbor activating mutations in the RAS-MAPK pathway, including BRAF V600E and NRAS Q61L/R, as well as the loss of NF1 in a subset of cases." (PMID 27130733, 2016). "Melanomas frequently harbor mutations in oncogenes like BRAF, NRAS (neuroblastoma RAS viral oncogene homolog), KIT (v-kit Hardy–Zuckerman 4 feline sarcoma viral oncogene homolog) and tumor suppressors CDKN2A and PTEN." (PMID 26846696, 2016). "NRAS mutant melanoma cells treated with vemurafenib exhibit a paradoxical activation of the MAPK pathway due to CRAF/BRAF dimerisation and CRAF transactivation." (PMID 27447557, 2016). "In conclusion, we have discovered and characterized CRAF R391W as a novel oncogene for BRAF/NRAS wild type melanomas." (PMID 27273450, 2016). "We investigated the regulation of TERT expression in melanoma cell lines and our results show that promoter mutations render TERT expression dependent on MAPK activation due to oncogenic BRAF or NRAS mutations." (PMID 27449293, 2016). "This biological process is also necessary for NRAS-induced cellular transformation and for maintaining the NRAS-mutant melanoma tumor growth." (PMID 27608486, 2016). "P-Rex2 is also frequently mutated in melanoma, and a truncating mutant, E824*, has recently been shown to cooperates with NRAS to accelerate melanoma development in a mouse model." (PMID 27104658, 2016). "Both HDRA and PDX models derived from the BRAF-mutated melanoma showed significant response to BRAF and MEK inhibitors, and those derived from the NRAS-mutated melanoma showed a significant response only to the MEK inhibitor pimasertib." (PMID 26909610, 2016). "First, our results demonstrate that IFI6 expression is activated by oncogenic NRAS, which is necessary for oncogenic NRAS-induced transformation and melanoma tumor growth." (PMID 27608486, 2016). "Toward this end, we tested the response of NRAS-mutant melanoma cells to drugs that induce cytotoxicity by inducing DNA replication stress." (PMID 27608486, 2016). "Both the PI3K and MAPK pathways have been targeted using very effective small molecule inhibitors as a clinical approach to treat RAS-mutant cancers, including NRAS-mutant melanoma." (PMID 27608486, 2016). "Nelfinavir also sensitized NRAS mutant melanoma cells to MEK inhibition and reduced PAX3 and MITF expression, whereas no sensitization was seen in the KRAS mutant colon cancer cell line HCT116." (PMID 26977879, 2016).
melanoma (continued). "To this end, we performed a combination screen using a collection of well-characterized kinase inhibitors whose targets are known, against the NRAS-mutant melanoma cell line, SK-MEL2." (PMID 27152946, 2016). "MiR-146a was shown to be highly up-regulated by oncogenic BRAF and NRAS mutants frequently observed in melanomas." (PMID 26646588, 2016). "To answer this question, we knocked down the expression of IFI6 in the NRAS-mutant melanoma cell line YUGASP and performed a microarray analysis." (PMID 27608486, 2016). "In 22 (40%) patients melanomas were BRAF wild-type, 23 (42%) showed a BRAF mutation, and 10 (18%) a NRAS mutation." (PMID 27213536, 2016). "High and low NRAS and BRAF mutation frequencies, respectively, have implications for the diagnosis, and treatment of melanoma in NZ." (PMID 27191502, 2016). "We began our analysis using a simplified model in which we examined the behavior of INK4a-deficient and ARF-deficient mouse melanocytes infected with a retrovirus encoding oncogenic NRAS (NRASQ61K), which is mutated in 20% of human melanomas." (PMID 27846237, 2016). "Our study further suggests that PIK3CA mutations account for a small fraction of PI3K pathway activation and have a limited impact in interfering with the BRAF/NRAS-driven growth in melanoma." (PMID 25627962, 2015). "Resultant mitogen-activated protein kinase (MAPK) pathway signaling makes some melanomas susceptible to BRAF (BRAF V600 mutations), MEK1/2 (BRAF V600, L597, fusions; NRAS mutations), or other kinase inhibitors (KIT), respectively." (PMID 26084293, 2015). "This RAS-RAF-MEK-ERK pathway is constitutively activated in melanomas harboring mutations in oncogenes such as BRAF and NRAS, respectively mutated in about 50 % and 15 % of these tumors." (PMID 26204954, 2015). "A total of 245 tumor specimens (212 primary melanomas and 33 melanoma cell lines) was screened for mutations in BRAF, NRAS, and PIK3CA genes by automated direct sequencing." (PMID 25627962, 2015). "The effect of mTOR inhibitors was also minor compared to MEK inhibitors in NRAS mutant melanoma cells." (PMID 26544513, 2015). "Exposure to ultraviolet (UV) radiation induces C > T nucleotide changes at dipyrimidine sites which are responsible for high mutation rates observed in melanomas, particularly those wild-type for both BRAF and NRAS." (PMID 25544760, 2015). "Since BRAF and NRAS mutations are mutually exclusive in nearly all cases, it is widely recognized that about two-thirds of patients present a melanoma with activation of the MAPK pathway, carrying a mutated BRAF or NRAS gene." (PMID 26322273, 2015). "Videomicroscopy measurements were used to evaluate the effect of ZA treatment on migration in one BRAF mutant and PTEN wild-type, two BRAF mutant and PTEN-null, two NRAS mutant and two triple wild-type melanoma cell lines." (PMID 25646931, 2015). "In IPC-298 melanoma cells, displaying constitutively activated MAPK-signaling upon an activating NRAS p.Q61L mutation, MEK inhibition significantly decreased cellular hnRNP K levels." (PMID 26136337, 2015). "Activation of STAT3 serine-727 and tyrosine-705 phosphorylations is promoted by BRAF(V600E) activity, whereas MEK inhibition decreases STAT3 phosphorylation in NRAS-mutant melanoma." (PMID 26116372, 2015). "In a phase II trial 30 patients with NRAS mutant melanoma were treated with the MEK inhibitor MEK162." (PMID 26544513, 2015).
melanoma (continued). "Intriguingly, in an independent study, NRAS status was suggested as a new candidate biomarker for selecting melanoma patients for high-dose interleukin-2 treatment (HD IL-2)." (PMID 26305188, 2015). "Although HRAS plays a negligible role in melanoma, NRAS, which is activated in 15–20% of cutaneous melanoma, has strong functional overlap with the other RAS isoforms." (PMID 26000250, 2015). "Immediately downstream of RAFs, MEK is one of the main signaling nodes in the MAPK pathway and MEK inhibitors have shown significant growth inhibitory effects in some BRAF and NRAS mutant melanoma cells." (PMID 25645078, 2015). "Current melanoma research focuses on the contribution of miR dysregulation in malignant melanoma and its relation to BRAF and NRAS oncogenic mutations." (PMID 26116372, 2015). "Patients with NRAS mutant melanomas had thicker tumors at presentation and these tumors had greater rates of mitosis than BRAF mutant and WT melanoma." (PMID 26305188, 2015). "A review of literature reports that 14 % of mucosal melanomas harbor activating c-KIT mutations; 5 % showed BRAF mutation and 14 % oncogenic mutations in NRAS, which is much lower than the reported BRAF prevalence (56–59 %) in cutaneous melanoma." (PMID 26420268, 2015). "As of today, mutant NRAS has been far better investigated, mainly in melanoma but also in other cancers such as lung cancer and T-cell lymphoma." (PMID 26544513, 2015). "Studies on xenografts of a NRAS mutant human melanoma cell line indicated that shRNA knockdown of both BRAF and CRAF caused delay in the tumor formation." (PMID 25645078, 2015). "The in vitro and in vivo activity of LY2090314 in preclinical models suggests that the role of Wnt activators for the treatment of both BRAF and NRAS driven human melanoma should be further explored." (PMID 25915038, 2015). "Inhibition of MEK in NRAS mutant melanoma was also successful in a phase II trial and a large phase III trial is planned." (PMID 26544513, 2015). "Growth inhibition assays were performed with single agent or a combination of PRi and MEKi on a panel of 14 NRAS mutant human melanoma cell lines." (PMID 25645078, 2015). "The substantial outcome of this study is that MEK162 is the first agent to be active against NRAS-mutant melanoma." (PMID 26171394, 2015). "Reasonably the same pattern of endogenous or developing resistance can exist in NRAS mutant melanomas." (PMID 25645078, 2015). "We here assessed the prevalence of the coexistence of BRAF/NRAS and PIK3CA mutations in a series of melanoma samples." (PMID 25627962, 2015). "Although this stratification is relevant, controversy exists regarding the prognostic significance of classifying melanomas based only on BRAF and NRAS mutations." (PMID 25909218, 2015). "This is in accordance with mutations of NRAS that sensitize towards MEK inhibitors in different kind of tissues including lung cancer, neuroblastoma, melanoma and T-cell lymphoma." (PMID 26544513, 2015). "Autopsy of 7 NRAS and 17 NRAS-ΔPTEN mice carrying melanoma revealed the presence of lung metastasis in 1/7 and 8/17 mice, respectively." (PMID 26307673, 2015). "In order to explore the antitumor activity of prenylation inhibition we investigated the response to zoledronic acid treatment in thirteen human melanoma cell lines with known BRAF, NRAS and PTEN mutational status." (PMID 25646931, 2015). "We also found that few well-known melanoma biomarkers like NRAS, CDK4 and CCND1 are significantly rewired in different metastatic melanoma stages, even if not differentially expressed (in the particular stage)." (PMID 26558755, 2015). "In the case of NRAS mutant melanomas, a recent phase Ib/II clinical study with the combination of the MEK inhibitor MEK162 and a CDK4/6 inhibitor (LEE011) is being conducted (NCT01781572)." (PMID 25645078, 2015). "Melanoma is an aggressive form of skin cancer, with mutations in BRAF and NRAS genes occurring in ~50% and ~15% of tumors respectively." (PMID 25544760, 2015).
melanoma (continued). "Over activity of the RAS/RAF/MEK/ERK mitogen-activated protein kinase (MAPK) pathway is the hallmark of the majority of melanomas, which is frequently due to mutations in BRAF or NRAS in approximately 50% and 20% of cases, respectively." (PMID 25645078, 2015). "The frequency of concomitant KRAS or NRAS mutations found in a BRAF-mutated tumor was 4 of 33 (12 %) in NSCLCs, 3 of 34 (8.8 %) in CRCs, or 3 of 67 (4.5 %) in melanomas." (PMID 26498038, 2015). "The combination of PRi + MEKi can be an effective regimen for blocking proliferation of NRAS mutant melanomas when there is higher activity of the MAPK pathway and dependence of proliferation and survival on this pathway." (PMID 25645078, 2015). "It is of interest to note that somatic mutations in the BRAF and NRAS gene are mutually exclusive, thus constitutive activation of the MAPK pathway occurs in approximately 65–75% of all melanoma tumors." (PMID 26426340, 2015). "Two ongoing phase I/II clinical trials are proceeding in NRAS-mutant melanoma combining MEK inhibitors with CDK4/6 inhibitors with promising early results: 1) binimetinib and LEE011 and 2) trametinib and palbociclib." (PMID 25537510, 2015). "Most melanomas display aberrant activation of the mitogen activated protein kinase (MAPK) pathway, most frequently via oncogenic mutations affecting BRAF and NRAS." (PMID 26524482, 2015). "Molecular analyses have revealed that roughly 50% of melanomas harbor BRAF mutations, whereas NRAS mutations are observed in 15–20% of them." (PMID 26322273, 2015). "First, we studied human melanoma cell lines with BRAF-V600E mutation (A2058, SK-MEL-28, A375, UACC62 and UACC257) and NRAS-Q61R mutation (SK-MEL-2)." (PMID 26158630, 2015). "The PI3K pathway is another well-known pathway that plays an important role in NRAS-mutant melanomas." (PMID 25537510, 2015). "BRAF patients were slightly younger than NRAS and WT/WT; mean age at primary melanoma and at LM was respectively 50 ± 16 and 56 ± 16 years for BRAF, 55 ± 22 and 59 ± 20 years for NRAS and 55 ± 12 and 59 ± 11 years in WT/WT patients." (PMID 26305188, 2015). "Among the analysed melanomas, 12/245 (4.9%) samples presented the coexistence of PIK3CA and BRAF/NRAS mutations." (PMID 25627962, 2015). "The most common gene mutation in melanoma is BRAF and NRAS which accounted for 50% and 20%, respectively; both mutations increase activity of the MAPK pathway." (PMID 26664783, 2015). "In a phase II study, conducted by Ascierto and coworkers, the activity against BRAF- and NRAS-mutant melanomas has been proved." (PMID 26171394, 2015). "In melanomas, the MAPK pathway is frequently hyperactivated by mutations in the BRAF gene (approximately 50% of melanomas) but also in NRAS (18%), KIT (9%), HRAS (2%) or KRAS (2%) genes (COSMIC database)." (PMID 26098773, 2015). "Early clinical results are supportive of a potential increased antitumor effect achieved by combining a MEK inhibitor with a CDK4/6 inhibitor in patients with NRAS mutant melanoma." (PMID 25645078, 2015). "Our group has recently reported in vitro and in vivo studies testing a variety of small molecule inhibitors and their combinations in NRAS mutant melanoma cell lines." (PMID 25277205, 2014). "On the other hand, mutations in NRAS, a RAS family member and MEK1 have been shown to mediate acquired resistance to the mutant BRAF kinase inhibitor, vemurafenib, in melanoma cell lines." (PMID 25361007, 2014). "We were able to demonstrate that the combination of a MEKi and a PI3K/mTORi can reduce cell viability in NRAS mutant cancer cell lines other than melanoma." (PMID 25277205, 2014). "Usp5 knockdown overcame acquired vemurafenib resistance and sensitized BRAF and NRAS mutant melanoma cells to apoptosis initiated by MEK inhibitor, cytokines or DNA-damaging agents." (PMID 24980819, 2014).